INS (insulin)
Diseases named in the same sentence as INS in open-access papers (continued):
Sharing a sentence is not in itself a finding about the gene and the disease.
Insulin resistance (continued). "In contrast, in participants defined as having metabolic insulin resistance (obesity or metabolic syndrome), the effect of insulin seems to be vasoconstrictive, leading to impaired blood flow and glucose uptake." (PMID 39661465, 2024). "The effects of lauric acid on metabolic disorders in mice fed a high-fat diet have been explored and have revealed improvements in insulin and insulin resistance, for example, in one study, a high-fat diet containing 3% lauric acid was administered to mice." (PMID 39204141, 2024). "All of these regulators are important in NF-κB pathway amplification in T2D, which plays a vital role in the development of insulin resistance by increasing proinflammatory cytokine production, which interferes with insulin signaling." (PMID 39201652, 2024). "Insulin resistance in obesity is characterized by reduced insulin-triggered glucose transport and processing in both fat cells and skeletal muscle, along with ineffective regulation of glucose production in the liver." (PMID 39275332, 2024). "Lower fasting insulin levels indicated an improvement in insulin sensitivity and potentially a reduction in insulin resistance." (PMID 39770980, 2024). "T2D is characterized by chronic hyperglycemia resulting from a combination of insulin resistance and impaired insulin secretion." (PMID 38255264, 2024). "After FMT, fasting insulin levels in T2D mice decreased and insulin resistance improved, as well as the insulin sensitivity index (HOMA-IS)." (PMID 39061972, 2024). "TNF-α, IL-6, and leptin activate inhibitory molecules such as the suppressor of cytokine signaling 3 (SOCS3) and c-Jun NH2-terminal kinase (JNK) that suppress insulin signaling, thus resulting in insulin resistance." (PMID 38397916, 2024). "Such an example is selenium, which is suggested to promote insulin resistance because of the excess production of selenoproteins that interfere with insulin signaling." (PMID 38493875, 2024). "Type 2 diabetes is characterised by insulin resistance and an inadequate compensatory insulin secretory response, resulting in chronic hyperglycaemia." (PMID 38791405, 2024). "Insulin resistance arises when peripheral tissues, such as skeletal muscle, liver, and adipose tissue exhibit decreased sensitivity to insulin, resulting in impaired uptake and utilization of glucose." (PMID 40302954, 2024). "Dysfunctions in the insulin signaling cascade caused by advancing age, such as reduced insulin-stimulated tyrosine phosphorylation, are more severe in adipose tissue than in liver or muscle tissue, suggesting that adipose tissue may be a source of insulin resistance during aging." (PMID 39519454, 2024). "Exposure to glyphosate also induces skeletal muscle insulin resistance by modulating IRS-1/PI3K/Akt insulin signaling molecules, leading to the development of T2DM." (PMID 38902690, 2024). "The oral administration of hesperidin was observed to lower fasting glucose levels, alleviate insulin resistance in diabetic rats, and enhance insulin release in isolated pancreatic islets." (PMID 39459367, 2024). "HepG2 cells were induced by 18 mM of glucosamine for 18 h, and the insulin resistance model was established to explore the effect of GP on insulin resistance cells." (PMID 38921004, 2024). "Studies conducted on rats with T2D demonstrated that consuming water enriched with nitrate improved fasting glucose, insulin resistance, insulin sensitivity, and lipid profiles." (PMID 39328991, 2024). "Insulin resistance measured as glucose-to-insulin ratio and HOMA-IR were also significantly reduced." (PMID 38469011, 2024). "Chronic inflammation thus impairs insulin signaling in adipocytes, leading to insulin resistance and the development of metabolic disorders." (PMID 39839113, 2024).
Insulin resistance (continued). "The serum insulin concentration and homeostasis model assessment of insulin resistance (HOMA IR) at 2 h and 3 h after oral glucose powder in women from the OD-HA group and HA-PCOM group were significantly higher than those from the OD-PCOM group (p < 0.05)." (PMID 39109080, 2024). "Groups with fatty liver exhibited severe insulin resistance, as evidenced by elevated fasting blood glucose, insulin, C-peptide levels, and higher HOMA-IR values." (PMID 39439559, 2024). "A critical aspect of T2D development is the progressive decline in insulin sensitivity and β-cell function, as indicated by the homeostatic model assessment for insulin resistance (HOMA-IR) and HOMA-β indices, respectively." (PMID 39596044, 2024). "Numerous studies have demonstrated the efficacy of chronic insulin exposure in the induction of insulin resistance models in vitro." (PMID 39749015, 2024). "Metformin, an insulin sensitizer, has been extensively studied for its ability to inhibit the proliferation and invasion of lung cancer cells by enhancing insulin resistance and influencing metabolic pathways." (PMID 38449844, 2024). "We also observed inverse correlations between several PCs and LPCs and fasting plasma glucose and insulin, as well as the homeostatic model assessment for insulin resistance (HOMA-IR) and inflammatory markers such as IL6 and C-reactive protein (CRP)." (PMID 39195560, 2024). "It was found that the IP7 produced by IP6K1 induces the secretion of insulin by β-cells and simultaneously inhibits the Akt protein kinase that signals insulin levels in metabolic tissues, leading to hyperinsulinemia and insulin resistance." (PMID 38397389, 2024). "During the first year after chemotherapy, plasma insulin levels and insulin resistance remained high in the EBC patients." (PMID 39415181, 2024). "Insulin resistance (IR) occurs when a greater than normal amount of insulin is required for an appropriate physiologic response to serum glucose." (PMID 38474786, 2024). "Insulin resistance affects lipid metabolism by hindering the typical function of insulin in adipose tissue, leading to increased lipolysis and the discharge of free fatty acids into the bloodstream." (PMID 39574946, 2024). "Increased collagen deposition in the HF-fed MMP9−/− mice was accompanied by exacerbated cardiac insulin resistance with decreased glucose uptake in heart during an insulin clamp." (PMID 38908792, 2024). "Insulin and the homeostasis model assessment of insulin resistance (HOMA-IR), a measure of insulin resistance, showed positive modulations under the intermittent CR diet." (PMID 38425626, 2024). "The Homeostatic Model Assessment of Insulin Resistance (HOMA-IR) has been routinely used to assess insulin sensitivity." (PMID 39590330, 2024). "Inflammatory cytokines released by hepatic adipose tissue, such as tumor necrosis factor-alpha (TNF-α) and interleukin-6 (IL-6), can impair insulin signaling pathways, leading to insulin resistance." (PMID 39683601, 2024). "In individuals with insulin resistance, elevated insulin levels play a significant role in the initiation and progression of lung cancer." (PMID 38449844, 2024). "Insulin resistance (IR) is characterized by the compromised functionality and impaired regulation of insulin-mediated glucose metabolism within various tissues, representing an aberrant physiological condition." (PMID 38216931, 2024). "In obese individuals, the suppressive effect of insulin on lipolysis is insufficient, leading to elevated circulating levels of FFAs, a condition referred to as adipose tissue insulin resistance (ATIR)." (PMID 39377071, 2024). "Disruption of the IRS/PI3K pathway leads to decreased tissue sensitivity to the metabolic action of insulin - a state of insulin resistance (IR), which is characteristic of patients with type 2 diabetes (T2D), obesity and arterial hypertension." (PMID 38323106, 2024).
Insulin resistance (continued). "In people with type 2 diabetes, insulin secretion is progressively lost and insufficient to compensate for insulin resistance, the latter being a cardinal feature of type 2 diabetes." (PMID 37922013, 2024). "It is clinically characterized by insulin resistance, often followed by long periods of insulin dysregulation, culminating in impaired glucose utilization and the development of hyperinsulinemia." (PMID 38689728, 2024). "Immunosuppressive therapy reduces anti-insulin IgG autoantibodies, leading to short-term clinical improvement and improved insulin resistance, emphasizing their crucial role in the condition." (PMID 38469413, 2024). "Blueberry-derived exosome-like nanoparticles (BELNs) improved insulin resistance, reduced fasting glucose levels, and decreased serum insulin content in mice fed a high-fat diet." (PMID 39275255, 2024). "But, liver dysfunction is also the concomitant consequence of an altered insulin function (insulin resistance), also related to diet." (PMID 38396928, 2024). "There is an increasing consensus suggesting that acupuncture can reduce blood glucose levels in T2DM by improving insulin sensitivity, ameliorating insulin resistance, inhibiting pancreatic β-cell apoptosis, and modulating insulin signaling pathways." (PMID 39834366, 2024). "All participants underwent assessments for anthropometry, blood pressure, circulating fasting levels of glucose, lipids, insulin, and anti-HAdV-36 antibodies; additionally, the homeostatic model assessment of insulin resistance (HOMA-IR) was calculated." (PMID 38932214, 2024). "In GDM patients, Chi3l1 levels are correlated with glycated hemoglobin, fasting insulin, and homeostasis model assessment of insulin resistance (HOMA-IR)." (PMID 39769202, 2024). "The evidence that insulin resistance, a complication in which insulin is increased, is common in children with asthma and is associated with asthma-like symptoms in adults, has suggested an inverse association between blood levels of insulin and lung function." (PMID 39371928, 2024). "These substances are thought to exert their antihyperglycaemic action by inhibiting protein tyrosine phosphatase 1B (PTPase‐1B), an essential component of insulin signalling and insulin resistance." (PMID 38982323, 2024). "In T2D, insulin resistance is increased, resulting in increased blood insulin levels, and blood adiponectin levels are decreased." (PMID 38392186, 2024). "Lastly, LivARKO-HFD female mice maintained hepatic insulin sensitivity whereas LivARKO-HFD male mice displayed hepatic insulin resistance." (PMID 38425436, 2024). "Although T2DM is generally described as the result of an imbalance between increased insulin resistance and decreased insulin secretion, the mechanisms are very complex and depend on a variety of contributing factors." (PMID 38247531, 2024). "The experimental findings demonstrated a significant decrease in blood glucose levels, serum insulin levels, insulin resistance, and fructosamine levels in diabetic rats subjected to treatment with Ch and Pu." (PMID 38603728, 2024). "Juiced broccoli can treat T2DM by improving insulin secretion and insulin resistance in mice, FINS and ISI in mice treated with juiced broccoli are significantly reduced." (PMID 38254574, 2024). "O-BN decreased levels of glucose, HbA1c, and insulin and reduced the insulin resistance in contrast to many other diets which only decreased the HbA1c levels." (PMID 37513690, 2023). "In a human trial, oral supplementation of A. muciniphila improved insulin sensitivity and reduced insulinemia and plasma total cholesterol in overweight or obese individuals with insulin resistance." (PMID 37445852, 2023). "It is well known that people with both T2D and obesity develop insulin resistance in the liver, adipose tissue, and the skeletal muscle, characterized by reduced cellular response to insulin, leading to hyperglycemia." (PMID 37628901, 2023).
Insulin resistance (continued). "Branched-chain amino acids (BCAA) are also important in exacerbating insulin resistance and obesity and disrupting insulin action." (PMID 37048534, 2023). "Insulin resistance occurs when insulin is unable to facilitate the glucose uptake into skeletal muscle and adipose tissues through this translocation of GLUT4 to the cell membrane." (PMID 36672202, 2023). "Insulin sensitivity is a vital indicator of metabolic health, since cellular insulin resistance is increasingly recognized as a key contributor to the development of metabolic syndrome and type 2 diabetes." (PMID 36838862, 2023). "Myriocin treatment protected against deleterious changes in insulin sensitivity and other indicators of insulin resistance that were assessed." (PMID 38068958, 2023). "There is a possible explanation for the observed differences: PCOS is often associated with hyperinsulinemia and peripheral insulin resistance; moreover, it is well established that IGF1 acts similarly to insulin." (PMID 37658762, 2023). "Since they participate in insulin signaling, inositols are used as food supplements to improve insulin sensitivity in patients with insulin resistance or type 2 diabetes." (PMID 36615188, 2023). "The model describes insulin resistance development on three different biological levels: whole-body composition, plasma glucose and insulin, and intracellular adipocyte insulin signaling." (PMID 38044443, 2023). "It is likely that insulin resistance becomes evident as central adiposity increases in TS, and that this exacerbates the pre-existing defect in insulin secretion." (PMID 36875465, 2023). "Dietary carbohydrate intake induces insulin secretion, and overconsumption of carbohydrates leads to insulin resistance." (PMID 37960324, 2023). "Insulin resistance occurs as a consequence of insulin signaling pathway inhibition, resulting in hyperglycemia due to impaired insulin-mediated glucose uptake and enhanced gluconeogenesis." (PMID 36834930, 2023). "Insulin resistance (IR) is a condition whereby insulin-targeted tissues, e.g., adipose, liver, and muscle, encounter metabolic disorders, thus leading to metabolic syndrome diseases, non-alcoholic fatty liver disease (NAFLD), atherosclerosis, and T2DM." (PMID 37606429, 2023). "Fasting and 2 h glucose levels and fasting insulin were measured at 26–28 weeks gestation and 4–6 years post-pregnancy, with the derivation of homeostatic model assessment for insulin resistance (HOMA-IR)." (PMID 37892496, 2023). "A decreased response to insulin (i.e., insulin resistance) affects the use of glucose and thus plays a fundamental role in the physiological adaptation of dairy cows." (PMID 37561770, 2023). "Insulin resistance (IR) is defined as reducing tissue’s sensitivity to insulin, resulting in insufficient insulin secretion in the pancreas to regulate blood glucose levels." (PMID 37515018, 2023). "Although fasting glucose levels were similar in the two groups, patients had increased fasting insulin levels (13.4 ± 13.1 vs 7.6 ± 3.3 miu/L, P = 0.014), suggesting the presence of insulin resistance." (PMID 37253232, 2023). "Insulin resistance manifests itself as insensitivity to insulin and a higher level of insulin and glucose in the blood, eventually leading to impaired insulin signaling pathways and glucose metabolism." (PMID 36978970, 2023). "When insulin resistance develops, β-cells of islets increase their mass to increase insulin production and secretion as a compensatory mechanism." (PMID 37514146, 2023). "The pathogenic effects related to obesity are greatly attributed to dysregulated secretion of adipokines, which leads to decreased insulin sensitivity (insulin resistance) in peripheral tissues including skeletal muscle and the liver." (PMID 36831292, 2023).
Insulin resistance (continued). "Appropriately, much of the research on insulin resistance and hyperinsulinemia revolves around insulin’s cardiometabolic roles in the development of type 2 diabetes, hypertension, and atherosclerosis, among others." (PMID 38068958, 2023). "As persistent hyperinsulinemia often leads to insulin resistance, we next tested insulin tolerance in these cohorts." (PMID 37188647, 2023). "Serum insulin levels significantly decreased, and insulin resistance improved (0.001) suggesting enhanced insulin sensitivity and better metabolic health." (PMID 38137679, 2023). "Type 2 diabetes (T2D) accounts for >90% of the total number of diabetic patients, which is predominantly induced by two main factors: insulin resistance (IR) and abnormal insulin secretion by pancreatic β-cells." (PMID 37025162, 2023). "While insulin resistance increases with aging and thus is generally unfavorable, klotho’s role in inhibiting the insulin/IGF-1 pathway is to decrease lipid overload since lipid-laden cells are vulnerable to lipid-induced programmed cell death." (PMID 37746149, 2023). "This process prevents the damaging effects of sugar-protein interactions, which can disrupt insulin signaling and lead to insulin resistance." (PMID 38089049, 2023). "Aloe-emodin demonstrated its capability to diminish TNF-α and IL-6 production while suppressing the NF-κB pathway, thereby restoring insulin signaling and ameliorating insulin resistance." (PMID 38053837, 2023). "For magenta module genes, the top enriched terms in the KEGG pathway databases were “Insulin signaling pathway” (adjusted p-value = 0.008) and “Insulin resistance” (adjusted p-value = 0.04)." (PMID 37205656, 2023). "Adipose tissue specific insulin resistance index (Adipo-IR) was calculated by fasting serum insulin and free fatty acids and categorized into 5 groups according to the quintiles." (PMID 38041145, 2023). "SFD consumption increased energy intake and was accompanied by the development of obesity and insulin resistance, as evidenced by the simultaneous increase in blood glucose and insulin levels and a decrease in glucose tolerance." (PMID 36982684, 2023). "Although plasmatic insulin levels were similar in the four experimental groups, diabetic animals had insulin resistance (p<0.01)." (PMID 34623540, 2023). "Using fasting serum insulin and glucose, we calculated insulin resistance and pancreatic beta cell function by homeostatic modelling (HOMA IR and HOMA%β respectively)." (PMID 37502917, 2023). "Among men, the plasma level is 25(OH)D and correlates with serum insulin levels, insulin resistance, and serum TG levels." (PMID 37239168, 2023). "Adding support to this, our findings revealed a substantial increase in levels of blood glucose and serum insulin after 16 weeks of WD exposure, indicating the development of insulin resistance." (PMID 37744933, 2023). "Metformin lowers glucose concentration by reducing insulin resistance, increasing glucose uptake from the periphery to skeletal muscles, enhancing insulin sensitivity, and decreasing gluconeogenesis and glucose production in the liver." (PMID 36811724, 2023). "Vaspin (also serpin A12) is an inhibitor of serine protease, which acts as an insulin-sensitizing adipocytokine, that is increased in obese patients, promoting insulin resistance and decreasing glucose tolerance." (PMID 38138997, 2023). "Type 2 diabetes is often preceded by a long period of prediabetes, characterized by insulin resistance and impaired insulin secretion." (PMID 37005925, 2023). "Serum homocysteine, insulin, homeostatic model assessment of insulin resistance (HOMA-IR), and hs-CRP were assayed." (PMID 36751256, 2023). "Insulin resistance refers to insulin-induced tissue damage, such as facilitating glucose absorption and inhibiting glycogen metabolism in adipocytes and skeletal muscle cells." (PMID 37791070, 2023).